Y_RNA (Y RNA )
Gene: Miscellaneous RNA gene on chromosome 18 (31,382,317 to 31,382,430, forward strand). Ensembl gene ENSG00000207240.
Homologues: Orthologues: chimpanzee Y_RNA (100% identical), macaque Y_RNA (89% identical). Paralogues in human: Y_RNA (88% identical), RNY1P5 (86% identical), Y_RNA (86% identical), Y_RNA (85% identical), Y_RNA (84% identical), Y_RNA (83% identical), Y_RNA (82% identical), Y_RNA (81% identical), Y_RNA (80% identical), RNY1 (79% identical), RNY1P14 (79% identical), Y_RNA (79% identical), and 95 more.